LRWD1 (leucine rich repeats and WD repeat domain containing 1)
Description:
Required for G1/S transition. Recruits and stabilizes the origin recognition complex (ORC) onto chromatin during G1 to establish pre-replication complex (preRC) and to heterochromatic sites in post-replicated cells. Binds a combination of DNA and histone methylation repressive marks on heterochromatin. Binds histone H3 and H4 trimethylation marks H3K9me3, H3K27me3 and H4K20me3 in a cooperative manner with DNA methylation. Required for silencing of major satellite repeats. May be important ORC2, ORC3 and ORC4 stability.
Synonyms: CENP-33; ORCA; DKFZp434K1815
Tractability: PROTAC: UniProt records ubiquitination sites on it; ubiquitination databases record sites on it; its protein half-life has been measured.
Gene: Protein-coding gene on chromosome 7 (102,464,939 to 102,473,507, forward strand). Ensembl gene ENSG00000161036.
Subcellular location: Nucleus; Chromosome, centromere; Chromosome, telomere; Cytoplasm, cytoskeleton, microtubule organizing center, centrosome; Chromosome, centromere, kinetochore
Subcellular location (Human Protein Atlas): Nucleoli; Nucleoli rim; Nucleoplasm; Vesicles
Gene Ontology:
Molecular function: chromatin binding; histone H3K27me3 reader activity; methyl-CpG binding; protein binding
Biological process: chromatin organization; establishment of protein localization to chromatin; DNA replication initiation
Cellular component: chromosome, telomeric region; kinetochore; nuclear origin of replication recognition complex; nucleolus; nucleoplasm; nucleus; pericentric heterochromatin; centrosome; chromosome, centromeric region
Genetic constraint (gnomAD): Loss-of-function variants: 76 observed, 68.02 expected, observed/expected ratio (o/e) 1.12, 90% interval 0.93 to 1.35. The synonymous counts are far from expectation, so gnomAD's model fits this gene poorly and the ratio says little. Missense variants: 917 observed, 806.11 expected, observed/expected ratio (o/e) 1.14, 90% interval 1.08 to 1.2. Synonymous variants: 487 observed, 358.07 expected, observed/expected ratio (o/e) 1.36, 90% interval 1.26 to 1.47.
Homologues: Orthologues: chimpanzee LRWD1 (99% identical), macaque LRWD1 (98% identical), dog LRWD1 (88% identical), pig LRWD1 (87% identical), guinea pig LRWD1 (83% identical), rat Lrwd1 (78% identical), mouse Lrwd1 (78% identical), rabbit LRWD1 (77% identical), tropical clawed frog lrwd1 (46% identical), zebrafish lrwd1 (41% identical), Caenorhabditis elegans lron-7 (8% identical). Paralogues in human: OPTC (10% identical).
Diseases named in the same sentence as LRWD1 in open-access papers:
LRWD1 is named in the same sentence as 8 diseases in open-access papers, as found by Europe PMC text mining. Sharing a sentence is not in itself a finding about the gene and the disease. The quoted sentences say what the papers report.
asthenozoospermia (1 paper, 2021). "Previous studies indicated that the sperm samples of asthenozoospermia, teratozoospermia, and asthenozoospermia have significantly lower LRWD1 expression than normal subjects." (PMID 34011267, 2021). "Also, the level of LRWD1 at the sperm neck was significantly reduced with a defective neck or tail in the patients with asthenozoospermia, teratozoospermia, and asthenoteratozoospermia." (PMID 34011267, 2021). "Furthermore, low expression levels of LRWD1 were observed in asthenozoospermia, teratozoospermia, asthenoteratozoospermia patients." (PMID 34011267, 2021).
Ewing sarcoma (1 paper, 2020). A small round cell tumor that lacks morphologic, immunohistochemical, and electron microscopic evidence of neuroectodermal differentiation. "LRWD1-regulated transcriptional activity of EWSR1-FLI1 is associated with poor prognosis of patients with Ewing’s sarcoma." (PMID 32899796, 2020).
Infertility (1 paper, 2021). "Based on these results, the methylation status of LRWD1 promoter may serve as a novel molecular diagnostic marker or a therapeutic target in males’ infertility." (PMID 34011267, 2021).
male infertility (1 paper, 2021). The inability of the male to effect fertilization of an ovum after a specified period of unprotected intercourse. "Thus, the methylation status of LRWD1 promoter may serve as a novel molecular diagnostic or therapeutic target in male infertility." (PMID 34011267, 2021).
testicular cancer (1 paper, 2024). A primary or metastatic malignant neoplasm that affects the testis. "Our previous study demonstrated the impact of LRWD1 on testicular cancer development; however, the underlying mechanisms remain unclear." (PMID 38385979, 2024). "Recently, we reported that autophagy is activated in LRWD1-deficient testicular cancer cells." (PMID 38385979, 2024). "Previous studies have demonstrated the impact of LRWD1 on testicular cancer development; however, the underlying mechanisms remain unknown." (PMID 38385979, 2024). "This is the first time that the role of LRWD1 in cell behaviors has been revealed during testicular cancer development, and a miRNA, miR-320a, was found to regulate the expression and activity of LWRD1 and subsequent cell behaviors." (PMID 38385979, 2024). "In that case, the regulation of miR-320a/LRWD1 was also involved in oxidative adaptation, so the potential participation of miR-320a/LRWD1 in the Warburg effect of testicular cancer cells is interesting and is worthy of investigation." (PMID 38385979, 2024). "This study supports the targeting of LRWD1 or miR-320a to reduce testicular cancer progression." (PMID 38385979, 2024). "We suspect that this abnormal phenomenon may be due to the interaction between miR-320a and LRWD1, a unique regulatory factor in testicular cancer cells." (PMID 38385979, 2024). "In our case, the expression of miR-320a, LRWD1 and NRF2 was increased, which is conducive to the survival of testicular cancer cells." (PMID 38385979, 2024). "The results indicate that miR-320a and LRWD1 are increased in the face of oxidative stress, which is conducive to the growth of NT2D1 testicular cancer cells." (PMID 38385979, 2024). "When cells lacked LRWD1, autophagy inhibition via chloroquine or bafilomycin A1 promoted the death of testicular cancer cells." (PMID 38385979, 2024).
carcinoma (2 papers, 2021 to 2024). A malignant tumor arising from epithelial cells. "However, the underlying mechanism regarding the role of LRWD1 in carcinoma cells remains unclear." (PMID 38385979, 2024). "In the current study, we aimed to reveal more information on the biological function of LRWD1 in regulating cell function and its regulatory effects on carcinoma cells." (PMID 38385979, 2024). "Our previous report showed that LRWD1 plays an important role in maintaining the survival of human testicular embryonic cancer cells and promotes cell proliferation and that its related mechanisms are worthy of further study." (PMID 38385979, 2024). "From this perspective, targeting miR-320a or LRWD1 seems to be a promising antitesticular cancer treatment strategy." (PMID 38385979, 2024).
LRWD1 also shares sentences with these, for which no sentence is quoted: teratozoospermia (1 paper); testicular embryonic carcinoma (1).